WWC2 (WW and C2 domain containing 2)
Description:
Regulator of the Hippo signaling pathway, also known as the Salvador-Warts-Hippo (SWH) pathway. Enhances phosphorylation of LATS1 and YAP1 and negatively regulates cell proliferation and organ growth due to a suppression of the transcriptional activity of YAP1, the major effector of the Hippo pathway.
Synonyms: BOMB; FLJ22029
Tractability: PROTAC: ubiquitination databases record sites on it; its protein half-life has been measured.
Gene: Protein-coding gene on chromosome 4 (183,099,126 to 183,320,777, forward strand). Ensembl gene ENSG00000151718.
Subcellular location: Cytoplasm, cytosol
Subcellular location (Human Protein Atlas): Microtubules
Gene Ontology:
Molecular function: kinase binding; molecular adaptor activity; protein binding; signaling adaptor activity
Biological process: hippo signaling; negative regulation of cell population proliferation; negative regulation of hippo signaling; negative regulation of organ growth; negative regulation of transcription by RNA polymerase II; cell migration; regulation of DNA-templated transcription; regulation of hippo signaling
Cellular component: cytoplasm; cytosol
Genetic constraint (gnomAD): Loss-of-function variants: 88 observed, 111.29 expected, observed/expected ratio (o/e) 0.79, 90% interval 0.67 to 0.94. The upper end of that interval is the gene's LOEUF score, 0.94, which puts it in group 4 of 6, group 1 being the genes least tolerant of losing a copy. Missense variants: 1,300 observed, 1,252.1 expected, observed/expected ratio (o/e) 1.04, 90% interval 0.99 to 1.09. Synonymous variants: 505 observed, 478.96 expected, observed/expected ratio (o/e) 1.05, 90% interval 0.98 to 1.13.
Homologues: Orthologues: chimpanzee WWC2 (98% identical), macaque WWC2 (97% identical), dog WWC2 (91% identical), rat Wwc2 (87% identical), guinea pig WWC2 (87% identical), mouse Wwc2 (86% identical), rabbit WWC2 (79% identical), pig WWC2 (79% identical), tropical clawed frog wwc2 (71% identical), Drosophila melanogaster kibra (31% identical). Paralogues in human: WWC1 (49% identical), WWC3 (44% identical).
Diseases named in the same sentence as WWC2 in open-access papers:
WWC2 is named in the same sentence as 14 diseases in open-access papers, as found by Europe PMC text mining. Sharing a sentence is not in itself a finding about the gene and the disease. The quoted sentences say what the papers report.
hepatocellular carcinoma (5 papers, 2017 to 2022). A malignant tumor that arises from hepatocytes. "Down-regulation of WWC2 has been reported to associated with advanced hepatocellular carcinomas (HCCs)." (PMID 30042827, 2018). "Furthermore, WWC2 inhibits the metastasis of hepatocellular carcinoma by negatively modulating the Hippo pathway." (PMID 35799607, 2022). "This study aimed to clarify the biological function and mechanism of action of WWC2 in hepatocellular carcinoma (HCC)." (PMID 28815883, 2017).
lung adenocarcinoma (4 papers, 2021 to 2026). A carcinoma that arises from the lung and is characterized by the presence of malignant glandular epithelial cells. "Similar with our findings, downregulation of WWC2 by miR-21-5p contributes to progression of lung adenocarcinoma, while upregulation of WWC2 caused by loss of miR-10a reverses the induction of EMT in pancreatic cancer stem cells." (PMID 35799607, 2022). "In this study, the expression levels of miR-589-3p and WWC2 were analyzed using The Cancer Genome Atlas lung adenocarcinoma (TCGA-LUAD) datasets via the UALCAN platform." (PMID 42122145, 2026). "It is reported that WWC2, belonging to the WWC protein family, exerts tumor-suppressing function in lung adenocarcinoma through negatively regulating the Hippo signaling pathway." (PMID 35799607, 2022).
pancreatic cancer (3 papers, 2021 to 2022). "For instance, WWC2 can reverse epithelial-mesenchymal transition (EMT) and block stemness maintenance of pancreatic cancer stem cells through inhibiting the Hippo signaling pathway." (PMID 35799607, 2022).
breast carcinoma (2 papers, 2018 to 2021). "Accordingly, the correlation between expression of WWC2/WWC3 and clinical features of breast cancer must be further determined." (PMID 30042827, 2018).
autoimmune disease (1 paper, 2022). A disorder resulting from loss of function or tissue destruction of an organ or multiple organs, arising from humoral or cellular immune responses of the individual to their own tissue constituents. "The hippo signalling pathway, with WWC2 as one of its key components, features critical functions in the innate immune responses against pathogens and in autoimmune diseases." (PMID 35748965, 2022).
cervical cancer (1 paper, 2022). A primary or metastatic malignant neoplasm involving the cervix. "Taken together, miR-146a-5p carried by EVs accelerated the metastasis of cervical cancer by inhibiting WWC2." (PMID 35799607, 2022). "In this study, we provided evidence that the miR-146a-5p carried by cervical cancer cells-derived EVs activated the Hippo-YAP signaling pathway through WWC2 to affect actin dynamics and promote cervical cancer metastasis." (PMID 35799607, 2022). "All in all, miR-146a-5p delivered by EVs contributed to cervical cancer metastasis through WWC2-mediated Hippo-YAP pathway." (PMID 35799607, 2022). "In conclusion, miR-146a-5p activated the Hippo-YAP signaling pathway through targeting WWC2 in cervical cancer cells." (PMID 35799607, 2022). "Collectively, WWC2 suppressed cervical cancer metastasis through blocking the Hippo-YAP pathway." (PMID 35799607, 2022). "Therefore, miR-146a-5p carried by cervical cancer cells-secreted EVs activated the Hippo-YAP pathway through inhibition of WWC2." (PMID 35799607, 2022). "Hence, miR-146a-5p could limit WWC2 expression in cervical cancer cells." (PMID 35799607, 2022).
gastric cancer (1 paper, 2026). A primary or metastatic malignant neoplasm involving the stomach. "The two loci (DOCK10 and FCN1-FCN2) replicated from CoGaPro1, and the 11 loci replicated from CoGaPro2 (CDK15, CROCC2-SNED1, TLR2-RNF175-SFRP2, WWC2, RELN, ZMYM5-ZMYM2, KLF12, SKAP1, CABLES2, and MIR630) gave further support for these genes being associated with a risk of CRC and gastric cancer." (PMID 41516419, 2026).
tumor (9 papers, 2017 to 2026). "Moreover, loss of WWC2 expression was significantly associated with advanced clinicopathological features, including venous infiltration, larger tumour size and advanced TNM stage." (PMID 28815883, 2017). "This review synthesizes current evidence demonstrating that WWC1, WWC2, and WWC3 exert context-dependent effects across malignancies, with WWC2 consistently functioning as a tumor suppressor while WWC1 and WWC3 display tissue-specific variability." (PMID 41727322, 2026). "From the results, it is evident that FAM225B and WWC2- AS2 are highly expressed in multiple tumor cell lines." (PMID 38334964, 2024). "It has been reported that WWC2 gene can inhibit tumor metastasis, while NOVA1 usually plays an oncogenic role." (PMID 35799607, 2022). "In vivo data demonstrated that EVs-carried miR-146a-5p promoted tumor metastasis through the WWC2/YAP axis." (PMID 35799607, 2022). "Recent reports have indicated that WWC1 and WWC2 can function as tumor suppressor molecules in lung cancer." (PMID 33837178, 2021). "WWC2 is shown as an anti-oncogene in human cancers that can be mediated by tumor-promotive miRNAs." (PMID 35799607, 2022). "Retrospective clinical association analysis using the Pearson chi‐squared test revealed decreased WWC2 expression in HCC was positively associated with tumour size (P = 0.030), venous infiltration (P = 0.006) and advanced tumour stage (TNM stage III + IV; P = 0.001)." (PMID 28815883, 2017). "Furthermore, Western blotting of 24 paired HCC tissues and adjacent non‐tumour tissues confirmed WWC2 protein expression was significantly decreased in HCC tissues compared with the paired adjacent non‐tumour tissues (P < 0.001)." (PMID 28815883, 2017). "Overall, this study indicates WWC2 functions as a tumour suppressor by negatively regulating the Hippo signalling pathway and may serve as a prognostic marker in HCC." (PMID 28815883, 2017). "Furthermore, we confirmed that WWC2 suppresses tumour progression by inhibiting the invasive ability of HCC cells." (PMID 28815883, 2017). "Moreover, positive WWC2 expression was associated with significantly better 5‐year overall survival and WWC2 was an independent prognostic factor for 5‐year overall survival, which suggests WWC2 functions as a tumour suppressor in HCC." (PMID 28815883, 2017). "First, we demonstrated WWC2 protein expression was significantly down‐regulated in HCC compared with the matched adjacent non‐tumour tissues, and the absence of WWC2 expression was significantly associated with larger tumour size, venous infiltration and advanced TNM tumour stage." (PMID 28815883, 2017). "Multivariate Cox regression indicated that, in addition to tumour stage (TNM stage III + IV; P = 0.015) and the number of tumour nodules (P = 0.041), WWC2 expression was an independent prognostic factor for overall survival in HCC (P = 0.003)." (PMID 28815883, 2017). "Certain assays of tumor suppression show a mutual requirement for PTPN14 and WWC1 (KIBRA), but potential contributions of WWC2 and WWC3 in the same assays have not been thoroughly tested." (PMID 38496413, 2024).
cancer (6 papers, 2012 to 2022). A tumor composed of atypical neoplastic, often pleomorphic cells that invade other tissues. "Since both ocular disease therapies, such as AMD and PDR, and beyond that, cancer treatment, use the protective and beneficial effects of anti-angiogenic therapies, the knowledge we gained about WWC2 as a crucial regulator is of great relevance and importance." (PMID 34070186, 2021). "Although the function of WWC1 has been studied intensively in cells and animal models, our understanding of the expression, biological behaviour and molecular mechanisms of action of WWC2 remains limited, particularly in human cancer." (PMID 28815883, 2017). "Emerging evidence shows the involvement of WWC2 in cancer metastasis." (PMID 35799607, 2022). "However, due to its high structural similarity to WWC1 and a comparable expression pattern, WWC2 is supposed to fulfil a regulatory role in the Hippo signaling pathway and human cancer, too." (PMID 33467643, 2021). "This study indicates WWC2 negatively regulates the Hippo pathway in HCC, implying WWC2 may represent a candidate target protein for cancer therapeutics." (PMID 28815883, 2017). "However, the expression and clinicopathologic significance of WWC2 in cancer are poorly characterized." (PMID 28815883, 2017). "Considering the structural similarities and putative redundant functions of all three WWC protein family members, WWC2 and WWC3 are supposed to play a WWC1-comparable role in human cancer." (PMID 33467643, 2021). "This review has been designed to provide an update on the published data linking WWC1, WWC2 and WWC3 to cancer, with a focus on Hippo pathway-dependent mechanisms." (PMID 33467643, 2021). "A hepatocyte-specific KO of Wwc1 and Wwc2, but not of a single WWC protein, leads to liver overgrowth and subsequent carcinoma formation in mice." (PMID 33483469, 2021).
WWC2 also shares sentences with these, for which no sentence is quoted: colorectal cancer (1 paper); lung carcinoma (1); metastatic tumors (1); myeloma (1); pulmonary hypertension (1).